RN7SL591P (RNA, 7SL, cytoplasmic 591, pseudogene)
Gene: Miscellaneous RNA gene on chromosome 10 (62,350,006 to 62,350,297, forward strand). Ensembl gene ENSG00000240940.
Homologues: Orthologues: chimpanzee Metazoa_SRP (99% identical), macaque Metazoa_SRP (83% identical). Paralogues in human: RN7SL1 (76% identical), RN7SL2 (75% identical), RN7SL566P (75% identical), RN7SL803P (75% identical), RN7SL3 (74% identical), RN7SL822P (74% identical), RN7SL296P (73% identical), RN7SL45P (73% identical), RN7SL507P (73% identical), RN7SL543P (73% identical), RN7SL546P (73% identical), RN7SL130P (73% identical), and 704 more.